KDM2A (lysine demethylase 2A)
Diseases named in the same sentence as KDM2A in open-access papers (continued):
Sharing a sentence is not in itself a finding about the gene and the disease.
cancer (continued). "KDM2A mRNA expression was around 2.59-fold higher in ccRCC samples than that in para cancer samples with a significant difference (P < 0.05)." (PMID 34391411, 2021). "IHC analysis revealed that KDM2A protein was predominantly located in the cell nucleus and ccRCC samples had significantly higher KDM2A expression levels than para cancer tissues." (PMID 34391411, 2021). "Cancer-derived cytokines stimulated KDM2A expression in normal fibroblasts and transformed them into CAFs." (PMID 33024266, 2021). "The numbers of senescent fibroblasts were dramatically reduced in the tumours generated by co-injection of the KDM2A-depleted fibroblasts confirming our cell-based finding that cancer cell-released cytokines induced the senescence of CAFs via KDM2A." (PMID 33024266, 2021). "Metformin, which is suggested to have anti-cancer effects, activates KDM2A to reduce rRNA transcription and proliferation of cancer cells." (PMID 33050392, 2020). "The presence of KDM2A in cancerous cells would give an advantage to the treatment of cancers though the activation of KDM2A to reduce rRNA transcription." (PMID 33050392, 2020). "In vertebrates, the KDM2 subfamily of KDMs consists of KDM2A and KDM2B; studies in the past decade have linked mutations of these KDM2 paralogs to a number of human cancers." (PMID 30233643, 2018). "Computational analysis of missense SNVs in KDM2A deposited in the public COSMIC and cBioPortal/TCGA cancer mutation databases indeed indicates an accumulation of cancer-associated SNVs in the region of the HP1 binding motif." (PMID 28180290, 2017). "To investigate the effect of KDM2A on cancer cell behaviors, we generated two independent KDM2A-depleted stable clones (231-3A1 and 231-2A2) from MDA-MB-231 cells by shRNA knockdown." (PMID 27029061, 2016). "First, the authors showed that KDM2A was stained in the myoepithelial cells while we found that KDM2A was expressed in cancer cells." (PMID 27029061, 2016). "As well as being overexpressed in certain cancers, KDM2A and KDM2B have also been found to be down-regulated in prostate cancer and glioblastoma respectively." (PMID 25145438, 2014). "KDM2A is overexpressed in a subset of non-small cell lung cancer patients and has been reported to drive cancer progression in these tumours through up-regulation of ERK1/2 (extracellular-signal-regulated kinase 1/2) signalling." (PMID 25145438, 2014). "Genetic alterations in JmjCs, including KDM2A, KDM2B, KDM4A, KDM4B, KDM42C and KDM5B, have all been linked to cancer progression and these enzymes have been suggested as chemotherapeutic targets." (PMID 25145438, 2014). "Of these, 50 were pathologically classified as normal/benign, 28 as DCIS and 57 as carcinoma; the levels of KDM2A were analyzed by immunohistochemistry." (PMID 25029110, 2014). "Although cancer-associated studies have not yet been conducted, KDM2A/7A-IN-1 is considered an inhibitor of KDM2A and KDM7A." (PMID 39938867, 2025). "Moreover, KDM2A contributes to metabolic rewiring of CSCs via regulation of PGC-1α and promotes stromal remodeling through activation of cancer-associated fibroblasts, further impairing immune and stromal surveillance in BC." (PMID 40941035, 2025). "Another recent report indicates that KDM2A inhibition may also be applicable to the treatment of a broader set of cancers that rely on alternative telomere maintenance, for which KDM2A is a critical factor." (PMID 39403928, 2024). "KDM2A is shown to be oncogenic in many cancer types including breast, gastric, and lung cancers." (PMID 39765675, 2024). "KDM2A is known to be upregulated in many cancers under the regulation of miRNAs." (PMID 37821959, 2023). "In addition, based on different context, KDM2A exhibits proliferative/antiproliferative properties in various cancers." (PMID 34079757, 2021).
cancer (continued). "In addition, based on IHC results, all the ccRCC samples were immunopositive, 90% of which showed a high expression of KDM2A protein, which was significantly higher than that in para cancer tissues." (PMID 34391411, 2021). "Among the predicted targets of miR-29b such as signal transducer and activator of transcription 3 (Stat3), cyclin-dependent kinase 6 (CDK6), lysine demethylase 2A (KDM2A) and Sirtuin-1 (SIRT-1), SIRT-1 was reported to be associated with chemoresistance in cancers." (PMID 29552311, 2018). "Given that KDM2A directly repressed NF-κB transcriptional activity via p65 demethylation, it would be anticipated that KDM2A activity may influence NF-κB driven cancer phenotypes." (PMID 28536364, 2017). "Cell culture studies have pointed to a role for KDM2A and other histone demethylases in the development of human cancers, but it is unclear whether KDM2A acts to promote or suppress carcinogenesis." (PMID 28806732, 2017). "The HP1-motif is enriched for cancer mutations and we find that an HP1 binding-deficient KDM2A mutant is inactive in an in vivo overexpression assay in zebrafish embryos underscoring the importance of HP1 binding for KDM2A function." (PMID 28180290, 2017). "The high cancer mutation density and the evolutionary conservation of the HP1 binding motif suggest an important role for the HP1 interaction in the biological function of KDM2A alongside the H3K36 demethylase activity." (PMID 28180290, 2017). "KDM2A has been reported to act as an oncogene in different types of cancer." (PMID 28304334, 2017). "We identified SOX2 as a direct transcriptional target of KDM2A to promote cancer stemness." (PMID 27029061, 2016). "These genes are involved in the regulation of cell cycle (CCND1, CDCA5, FOSL1, KDM2A, NUMA1, RHOD), apoptosis (FADD, ORAOV1), or the DNA damage response (DDB1, KAT/TIP60, MUS81, PACS1, RPS3), and several have been implicated in the HPV lifecycle and/or HPV-associated cancers." (PMID 40892869, 2025). "The growing evidence suggests that Kdm2a plays a key role in cell differentiation, apoptosis, and cellular proliferation via executing its H3K36 demethylase activities at target sites, while dysfunctions associated with Kdm2a have been reported across various tumors and cancers." (PMID 39940999, 2025). "Importantly, further studies may provide more gallic acid derivatives that activate KDM2A and reduce rRNA transcription, and reveal novel anti-cancer agents." (PMID 35053178, 2021). "Therefore, the concentration range of gallic acid to effectively activate KDM2A is limited, which may be an obstacle to applying this tumorigenic cell-specific activation of KDM2A for cancer treatment." (PMID 33050392, 2020). "To test whether any of the cancer mutations affect the interaction between KDM2A and HP1 we introduced several mutations found in the vicinity of the HP1 binding motif into our FLAG-GFP-KDM2A expression construct." (PMID 28180290, 2017). "We repressed KDM2A expression in the normal RMF-EG fibroblasts by shRNA and co-injected the control or KDM2A-depleted fibroblasts with MDA-MB-231 cancer cells into the fourth mammary fat pads of nude mice." (PMID 33024266, 2021). "Indeed, treatment of normal RMF-EG fibroblasts with IL-6 and TNF-α, two abundant cytokines in the conditioned medium of MDA-MB-231 cancer cells, increased KDM2A protein level in a dose-dependent manner suggesting these two cytokines may play a role in stimulating KDM2A expression in fibroblasts." (PMID 33024266, 2021). "Compared with para cancer tissues, ccRCC samples showed a higher KMD2A mRNA level and a larger proportion of high KDM2A expression (all P < 0.05)." (PMID 34391411, 2021). "Thus, the specific activation of KDM2A may be applicable to the treatment of cancers." (PMID 33050392, 2020). "As previously reported, overexpression of KDM1A and KDM2A in NSCLC cells increases cell proliferation and invasiveness and promotes cancer metastasis." (PMID 29619118, 2018).
cancer (continued). "However, the contribution of KDM2A to other cancers is largely unknown." (PMID 27029061, 2016). "Ductal cells from benign and carcinoma tissues stained weakly positive (p<0.001 and p<0.01) whereas ductal cells from DCIS showed moderate positivity for KDM2A (p<0.001)." (PMID 25029110, 2014). "KDM2A is known to play a role in the development of GBM in two different pathways, specifically through microRNAs (miRNAs), which are essential regulators of gene expression in human GBM and other human cancer types." (PMID 39765675, 2024). "Interestingly, 15 was identifiedas a potent inhibitor of the histone H3 lysine 36 JmjC KDM2A (IC50 63 nM), which is a potential cancer target." (PMID 34762429, 2021). "Overall, our results show that the gallic acid derivatives PG and EGCG activate KDM2A, consequently suggesting that the esterification of gallic acid does not impact its anti-cancer activity to a major extent." (PMID 35053178, 2021). "Thus, the role of KDM2A and KDM2B in tumorigenesis seems to be dependent on different types of cancers." (PMID 30233643, 2018). "These mutations appear to modulate and not completely disrupt the interaction between KDM2A and HP1 suggesting a deregulation rather than loss of function of KDM2A caused by certain cancer mutations." (PMID 28180290, 2017). "As shown in their figure, the KDM2A signal in tumor part was appeared in cancer cells but not myoepithelial cells." (PMID 27029061, 2016). "We found a strong positive correction (P<0.0001) between KDM2A and JAG1 in these cancer patients." (PMID 27029061, 2016). "Further, while recent studies demonstrated that KDM2A maintains the heterochromatic state by binding to HP1 proteins and repressing transcription of centromeric satellite repeats, very little information is available on the precise function of KDM2A, especially in different cancers." (PMID 25029110, 2014). "However, it has not yet been investigated whether PG and EGCG activate KDM2A to reduce rRNA transcription in cancer cells." (PMID 35053178, 2021).
tumor (41 papers, 2012 to 2026). "Clinicopathological association analysis demonstrated that stromal KDM2A expression was correlated with increased tumour size, lymph node invasion, clinical stage and histological grade." (PMID 33024266, 2021). "Univariate log-rank analysis for DSS and MeFS showed that high stromal KDM2A was associated with increased tumour size, lymph node invasion and clinical stage." (PMID 33024266, 2021). "In this study, we investigated the clinical significance of KDM2A in tumour stroma and tried to elucidate the underlying mechanism by which stromal KDM2A promotes breast tumorigenesis." (PMID 33024266, 2021). "Moreover, high KDM2A mRNA expression in ccRCC was associated with large tumor size, advanced TNM stage and a poor survival prognosis." (PMID 34391411, 2021). "KDM2A overexpression in NSCLC cells with low KDM2A levels increased cell proliferation and invasiveness (H460 and H2122 cells), while KDM2A KD abrogated tumour growth and invasiveness in NSCLC (H1792 cells) xenografts." (PMID 40943262, 2025). "SEMA6A-AS1 affects HCC progression by regulating SEMA6A mRNA stability, while UNC5B-AS1 promotes EMT and tumor metastasis via the miR-4306/KDM2A axis." (PMID 41431005, 2025). "KDM2A physically interacts with the tumor suppressor miR-132 promoter and inhibits its expression, effectively acting as a tumor activator." (PMID 39684425, 2024). "We already described the tumor promoting effect of cathepsin K, and of lysine demethylase Kdm2a in LC which stimulates Erk1/Erk2 signaling through epigenetic silencing of DUSP3." (PMID 38245882, 2024). "In our previous study, the transcriptional level of KDM2A was increased in normal fibroblasts after stimulation with tumor-derived inflammatory cytokines TNF-α and IL-6 and further drove the transformation of the cells into CAFs." (PMID 37821959, 2023). "CD163 is a known marker expressed in M2 macrophages, while KDM2A is highly expressed in both tumor cells and CAFs." (PMID 37821959, 2023). "As the target of Zinc-fingers and homeoboxes (ZHX2), a tumor suppressor, KDM2A is negatively correlated with ZHX2 in hepatoma cells." (PMID 36797239, 2023). "Analysis of tumor growth revealed that inactivation of KDM2A by sgK#1 or sgK#2 significantly inhibited the in vivo tumorigenicity, indicating that KDM2A is required for ALT-driven tumor propagation." (PMID 36991019, 2023). "In KDM2A-deficient cells, TET2 upregulation can induce the reactivation of two tumor-suppressive genes, epithelial cell adhesion molecule and e-cadherin located downstream of TET, and thus inhibiting cell migration and invasion." (PMID 35223782, 2022). "Collectively, our results proved that circFOXO3 sponges miR‐214 to up‐regulate the expression of KDM2A, thus promotes tumor progression in OSCC." (PMID 34117688, 2022). "To determine the function of KDM2A in circFOXO3‐miR‐214 mediated tumor growth, we co‐infected SCC‐4 cells with KDM2A siRNA and circFOXO3/miR‐214 inhibitor, and detected the invasiveness of SCC‐4 by transwell assay." (PMID 34117688, 2022). "Lastly, we performed xenograft tumor in nude mice to evaluate the effect of SP1 on the tumorigenesis of CRC cells in vivo through regulation of the TUG1/miR-421/KDM2A/ERK pathway." (PMID 35508523, 2022). "High KDM2A mRNA expression was more likely to occur in ccRCC tissues with tumor size > 7 cm (P = 0.005) and T3-T4 stage (P = 0.047)." (PMID 34391411, 2021). "Emerging studies have shown that the level of KDM2A expression is up-regulated in a variety of tumor cells and affects the biological behavior of tumor cells." (PMID 34391411, 2021). "According to the median ratio of KDM2A mRNA level (2.61) in tumor tissues, ccRCC patients were classified into the high and low KDM2A mRNA expression groups." (PMID 34391411, 2021). "Consistently knockdown of KDM2A significantly decreased tumor growth and invasive capabilities in mouse xenograft models." (PMID 33670008, 2021).
tumor (continued). "High KDM2A mRNA expression was positively correlated with tumor size and TNM stage, and had an adverse effect on the overall survival of ccRCC patients." (PMID 34391411, 2021). "Upregulation of TET2 in the KDM2A-depleted cells induces the re-activation of two TET downstream tumor suppressor genes, epithelial cell adhesion molecule (EpCAM) and E-cadherin, and inhibits migration and invasion." (PMID 28785073, 2017). "Fifty percent (101/202) of tumor tissues exhibited high expression of KDM2A with strong nuclear staining and light cytoplasmic staining." (PMID 27029061, 2016). "In this study, we provide evidence that JAG1 is a direct target of KDM2A and is important for KDM2A to promote tumor stemness and angiogenesis." (PMID 27029061, 2016). "In addition, Pearson’s correlation coefficient analysis indicated the inverse correlation between KDM2A and miR-302a expression in the tumor samples." (PMID 35181676, 2022). "SP1 silencing suppressed the tumor growth, which was reversed by overexpression of KDM2A." (PMID 35508523, 2022). "This study is the first to report that KDM2A is important for OSCC tumor progression and invasion." (PMID 34117688, 2022). "KDM2A helps to promote tumor invasiveness and proliferation of OSCC." (PMID 34117688, 2022). "Furthermore, we analyzed the relative expression of miR‐214/KDM2A and circFOXO3/KDM2A in OSCC tumor tissues and found the consistent correlation of both by Pearson." (PMID 34117688, 2022). "Moreover, we demonstrated that depletion of KDM2A resulted in a significant decrease in tumor size compared to that in the vehicle control." (PMID 35697678, 2022). "As well as KDM2A and KDM2B, which have K3K36me2 and H3K4me3 as their substrate, where its deregulation is associated with increased proliferation of stem cells and tumor growth and metastasis among other processes such as cell proliferation and drug resistance, among others." (PMID 35480330, 2022). "In addition, KDM2A protein level was increased in the CAFs isolated from tumour tissue comparing with the normal fibroblasts isolated from non-tumour part." (PMID 33024266, 2021). "Moreover, an elevated percentage of high KDM2A mRNA expression was markedly demonstrated in ccRCC tissues with tumor size > 7 cm and T3-T4 stage." (PMID 34391411, 2021). "The in vivo tumour-promoting activity of stromal KDM2A was confirmed by animal study." (PMID 33024266, 2021). "However, KDM2A appears to play a tumor suppressive role in colon cancer, and similarly, KDM2B is implicated to play a tumor suppressor role in lymphoma and brain cancer." (PMID 30233643, 2018). "Finally, inhibition of KDM2A significantly decreased tumor growth and angiogenesis in orthotopic animal experiments." (PMID 27029061, 2016). "In addition to increase of stemness, we also demonstrated the promotion of tumor angiogenesis by KDM2A via PDGFA and JAG1." (PMID 27029061, 2016). "In addition to alteration in cell proliferation, our GSEA analysis demonstrated that inhibition of KDM2A attenuates tumor angiogenesis and mRNA expression of several genes in the NOTCH signaling pathway including JAG1, NOTCH1, HEY1." (PMID 27029061, 2016). "Since breast MEPCs have tumor-suppressive and anti-angiogenic properties, we hypothesized that KDM2A could be contributing to some of these functions." (PMID 25029110, 2014). "Finally, to assess whether KDM2A is essential for in vivo ALT tumor cell growth, Saos2 cells transduced with sgCtrl or KDM2A-specific sgRNAs were subcutaneously grafted into immunocompromised recipient mice." (PMID 36991019, 2023). "Furtherly, we analyzed the correlations of KDM2A mRNA and protein expression with clinical features in ccRCC and found that the high expression of KDM2A mRNA was more likely to occur in ccRCC tissues with tumor size > 7 cm (P = 0.005) and T3-T4 stage (P = 0.047)." (PMID 34391411, 2021). "However, KDM2A has a complex and tissue-specific role in tumorigenesis and tumor progression." (PMID 34391411, 2021).